SSTR4 (somatostatin receptor 4)
Diseases named in the same sentence as SSTR4 in open-access papers:
SSTR4 is named in the same sentence as 58 diseases in open-access papers, as found by Europe PMC text mining. Sharing a sentence is not in itself a finding about the gene and the disease. The quoted sentences say what the papers report.
depression (10 papers, 2018 to 2024). "Several indirect and direct studies have demonstrated the association between SSTR4 and depression, which also relates to chronic stress." (PMID 38698013, 2024). "Studies on SSTR4 and stress or depression-like behavior have only reported Sstr4 mRNA expression in the brain, stress responsiveness and depression-like behavior in Sstr4 -deficient mice, and the potential of Sstr4 as a therapeutic target for anxiety and depressive disorders." (PMID 38698013, 2024). "In this study, we focus on SSTR4 that proved to be a promising target in the treatment of inflammation and pain-associated conditions (neuropathic pain, neurogenic inflammation, bronchial asthma, rheumatoid arthritis), Alzheimer’s disease, and depression." (PMID 35805885, 2022). "Among studies on SSTR4 and stress- or depression-like behavior, to our knowledge, the dynamics of SSTR4 expression outside the brain have yet to be investigated., and the results of the present study constitute novel findings." (PMID 38698013, 2024). "The somatostatin receptor subtype 4 (SSTR4) gene has emerged as a significant focus in the investigation of mental health disorders, including schizophrenia, depression, and bipolar disorder, with research implicating its involvement in their pathogenesis." (PMID 39055257, 2024). "The potential of SSTR4 as a therapeutic target for anxiety and depressive disorders has also been reported." (PMID 38698013, 2024). "Centrally, SSTR4 is involved in learning and memory processes and anxiety and depression-like behavior." (PMID 35805885, 2022). "Functional importance of SST4 in the central nervous system is illustrated by worse performance of Sstr4 knockout mice in models of anxiety and depression." (PMID 33806000, 2021). "SSTR4 has been shown to mediate anxiolytic and depression-like effects." (PMID 38698013, 2024). "Somatostatin 4 receptor (SSTR4) has been shown to mediate anxiolytic and depression-like effects." (PMID 38698013, 2024). "Moreover, preclinical studies indicate the potential of SSTR4 agonists as treatments for anxiety and depression, possibly through normalization of dysregulated neurocircuitry." (PMID 39055257, 2024). "Additionally, it has been shown that mice with Sst4 knockout showed increased anxiety and depression-like behavior, while J-2156 (a Sstr4 agonist) exerted anxiolytic- and antidepressant-like effects." (PMID 36344870, 2023). "Furthermore, the direction of methylation changes in the SSTR4 promoter region is disease-specific: hypomethylation is associated with the onset of bipolar disorder and schizophrenia, rather than major depressive disorder." (PMID 39055257, 2024). "In addition, the changes in SSTR4 expression dynamics observed in this study may reflect chronic stress-induced mental illnesses (e.g., anxiety and mood disorders) and depression-like behaviors, as the increase in plasma corticosterone levels does not persist in vivo after chronic-stress loading." (PMID 38698013, 2024). "However, there is no specific information regarding SSTR4 abnormalities in schizophrenia, major depressive disorder, or bipolar disorder." (PMID 39055257, 2024).
Anxiety (9 papers, 2018 to 2024). Intense feelings of nervousness, tension, or panic often arise in response to interpersonal stresses. "Thus, it is possible that SSTR4 expression levels fluctuate during mental illness (such as anxiety and mood disorders) and depressive behavior caused by chronic stress, including IPV and elder abuse." (PMID 38698013, 2024). "It was shown that SST INs and SSTR4 play regulatory roles in anxiety and mild stress-induced responses in the amygdala." (PMID 31873798, 2020).
Alzheimer disease (4 papers, 2018 to 2025). A progressive, neurodegenerative disease characterized by loss of function and death of nerve cells in several areas of the brain leading to loss of cognitive function such as memory and language. "In addition, experimental data suggest SSTR4 might represent important therapeutic targets for the treatment of Alzheimer’s disease and seizures, yet the direct evidence for the role of SSTR4 in alcoholism is still lacking." (PMID 35754825, 2022).
breast carcinoma (3 papers, 2006 to 2023). "The overexpression of SSTR1 and SSTR4 in MDA-MB-435S breast cancer cells resulted in a decrease in number of cells in the S phase upon receptor activation and associated with cell cycle arrest through dimerization between SSTR1/SSTR4." (PMID 38203605, 2023). "We found higher levels of expression of ErbB1 and lower levels of SSTR1, SSTR4 and ErbB3 in ERα – (MDA-MB-231) cells when compared to ER+ (MCF-7) breast cancer cells." (PMID 16519802, 2006).
meningioma (3 papers, 2021 to 2024). A generally slow growing tumor attached to the dura mater. "While the expression of SSTR4 was generally low in meningiomas when compared to other SSTRs, spinal tumor location showed the highest expression score (p = 0.0062)." (PMID 33899156, 2022). "In conclusion, all SSTRs, except SSTR4, are highly upregulated in meningiomas, supporting a crucial role of these receptors in the tumorigenesis of these tumors." (PMID 34830858, 2021). "In general, SSTRs expression was stronger in WHO grade 2 than WHO grade 1 meningiomas, except for SSTR4 that showed similar expression in both grades." (PMID 34830858, 2021). "All SSTRs, except SSTR4, were upregulated in our series of meningiomas." (PMID 34830858, 2021). "In feline meningiomas (n = 12), RNA expression of SSTR1, SSTR4, SSTR5 and SSTR2 was detected in 91%, 46%, 46% and 36% of samples, respectively; SSTR3 was not expressed." (PMID 39011594, 2024). "The distribution of SSTR1, SSTR4 and SSTR5 in feline meningiomas was similar to that of human meningiomas." (PMID 39011594, 2024). "• Feline meningiomas exhibited SSTR1, SSTR4, SSTR5 and SSTR2 expressions." (PMID 39011594, 2024). "Therefore, we analyzed the distribution of 5 somatostatin receptors (SSTR1, SSTR2A, SSTR3, SSTR4, SSTR5) in a large meningioma cohort including patients suffering from NF2 and higher grade meningiomas." (PMID 33899156, 2022). "SSTR4 was also negative in all normal meningeal tissues and was only upregulated in a few tumors pointing to the minor role of this receptor in meningiomas." (PMID 34830858, 2021).
pituitary adenomas (3 papers, 2018 to 2021). "Somatoprim, another second-generation SSA, is a multi-receptor targeting analog with a preference for SSTR2, SSTR4, and SSTR5, which was trialed in vitro on growth hormone (GH)-secreting pituitary adenomas." (PMID 33854479, 2021). "In 1994, Greenman and Melmed analyzed SSTR 3, SSTR4, and SSTR5 in 33 pituitary adenomas and SSTR1 and SSTR2 in 27 pituitary adenomas using RT-PCR, including 2 and 3 ACTH-producing adenomas, respectively." (PMID 30627156, 2018). "Gonadotroph and nonfunctioning pituitary adenomas had the highest mean SSTR4 expression (both 1.64, 95% CI 1.02–2.25 and 1.31–1.98, respectively) followed by PIT-1-positive adenomas (1.44, 95% CI 0.97–1.91)." (PMID 30627156, 2018). "Previous reports of SSTR mRNA expression in GH-secreting pituitary adenomas in humans describe SSTR5 > SSTR2 whereas SSTR1 and SSTR3 expression can be highly variable and SSTR4 expression is absent." (PMID 30620005, 2019). "Paraffin-embedded tumor samples of 88 corticotroph pituitary adenomas and 30 nonadenomatous pituitary biopsies were analyzed after processing into tissue microarrays and immunohistochemical staining for SSTR 1, SSTR2A, SSTR3, SSTR4, and SSTR5." (PMID 30627156, 2018).
adenoma (2 papers, 2018 to 2019). A neoplasm arising from the epithelium. "A total of 235 adenoma samples were stained for SSTR4 expression." (PMID 30627156, 2018).
alcohol dependence (2 papers, 2022 to 2025). Physical and psychological dependence on alcohol. "Linear regression was used to analyze the correlation between the methylation levels of SSTR4 promoter and the scores of alcohol dependence scales." (PMID 35754825, 2022).
alcohol use disorder (2 papers, 2022 to 2024). "Our previous study suggested abnormal methylation of SSTR4 in promoter region (cg14631053) as a risk for alcohol use disorder development." (PMID 39055257, 2024). "Previous studies have found that abnormal methylation of cg14631053 at the SSTR4 promoter region mediates the onset of alcohol use disorder." (PMID 39055257, 2024). "Considering our previous finding, this study offered transdiagnostic insights from abnormal methylation of SSTR4 promoter region for schizophrenia, bipolar disorder and alcohol use disorder." (PMID 39055257, 2024). "Nonetheless, abnormal methylation of cg01471923, first reported in patients with alcohol use disorder, has been replicated in patients with schizophrenia and bipolar disorder, expanding understanding of SSTR4 and providing transdiagnostic evidence for targeted clinical developments." (PMID 39055257, 2024). "According to this result, stressful events (higher values of LES and WSS) may contribute to alcohol use disorder and AD (higher value of AUDIT), and then influence the methylation of SSTR4 (hypomethylation)." (PMID 35754825, 2022).
schizophrenia (2 papers, 2024 to 2025). A major psychotic disorder characterized by abnormalities in the perception or expression of reality. "SSTR4 is a promising candidate biomarker, as our study implicated its role in modulating cognitive processes and demonstrated alterations in SSTR4 expression and function in schizophrenia patients, correlating with cognitive deficits." (PMID 39908289, 2025). "The methylation status of SSTR4 exhibits significant differences between healthy controls (ncontrol = 1,798) and patients with schizophrenia (ncase = 536) according to EWAS Open Platform, elucidating potential epigenetic mechanisms underlying the disease." (PMID 39908289, 2025). "Nevertheless, the clinical significance of SSTR4 in individuals with schizophrenia remains uncertain and warrants exploration." (PMID 39908289, 2025). "The observed differential DNA methylation of SSTR4 in specific tissues among healthy controls and individuals with schizophrenia provides valuable insights into potential epigenetic mechanisms associated with psychiatric disorders." (PMID 39908289, 2025). "It is important to note that no discernible differences were observed in the expression and methylation patterns of SSTR4 between males (n = 349) and females (n = 186) diagnosed with schizophrenia, as demonstrated in S1 and S2 Figs in S1 Appendix." (PMID 39908289, 2025). "In this study, leveraging publicly available data, we identified that changes in methylation of cg14631053 from the SSTR4 promoter region are involved in the development of bipolar disorder and schizophrenia." (PMID 39055257, 2024). "However, the role of genetic-epigenetic interactions involving SSTR4 in patients with schizophrenia remains unexplored." (PMID 39908289, 2025). "Consequently, this study seeks to investigate the role of SSTR4 methylation in patients with schizophrenia." (PMID 39908289, 2025). "These epigenetic alterations suggest that SSTR4 may play a role in the pathophysiology of schizophrenia, possibly through its impact on gene expression and consequent neural functions." (PMID 39908289, 2025). "SSTR4, a member of the somatostatin receptor family, is implicated in various neurological and psychiatric conditions, including cognitive function, AUD, and schizophrenia." (PMID 39908289, 2025). "In conclusion, SSTR4 promoter methylation may serve as a marker for identifying bipolar disorder and schizophrenia, providing insights into a transdiagnostic mechanism for precision medicine in the future." (PMID 39055257, 2024). "Furthermore, reduced SSTR4 expression in brain regions like the hippocampus and amygdala in schizophrenia patients and animal models may disrupt neural circuitry associated with aversion and reward processing." (PMID 39055257, 2024). "Incorporating SSTR4 as a biomarker could facilitate early detection, disease monitoring, and evaluation of cognitive-enhancing therapies, enabling personalized treatment approaches and potentially improving long-term outcomes for individuals with schizophrenia." (PMID 39908289, 2025). "SSTR4, a member of the somatostatin receptor family, has implications in various neurological and psychiatric conditions, encompassing cognitive function, AUD, and schizophrenia." (PMID 39908289, 2025). "While the direct relationship between methylation of SSTR4 and schizophrenia has not been explicitly studied, a substantial body of research has implicated aberrant DNA methylation patterns in the pathogenesis of this psychiatric disorder." (PMID 39908289, 2025). "Additionally, we explored other CpG sites within the SSTR4 gene, finding no statistically significant distinctions between cases (bipolar disorder, schizophrenia, or MDD) and healthy controls, with the exception of cg18197392 in bipolar disorder (p = 0.042)." (PMID 39055257, 2024).
type 2 diabetes (2 papers, 2018 to 2021). "The expression patterns of SSTRs in islet cells are altered in type 2 diabetes mellitus (T2DM), with diminished levels of SSTR1 and SSTR4 in α-cells and SSTR1-4 in δ-cells, which could further contribute to impaired somatostatin paracrine regulation in diabetes." (PMID 33494193, 2021).
Cognitive impairment (1 paper, 2025). Abnormal cognition is characterized by deficits in thinking, reasoning, or remembering. "The variation in methylation patterns in crucial brain regions and blood samples suggests the potential utility of SSTR4 methylation status as a peripheral biomarker for assessing both aging and cognitive impairment." (PMID 39908289, 2025).
corticotroph adenomas (1 paper, 2018). "Recurrent CD cases showed a significantly higher expression of SSTR1 (p = 0.0351) and SSTR4 (p = 0.0174) while SSTR5 ID scores were lower than in primary corticotroph adenomas (p = 0.0370)." (PMID 30627156, 2018). "While SSTR2 and SSTR4 were not detectable in corticotroph adenomas, one out of three cases showed expression of SSTR1 and one out of two for SSTR3 and SSTR5." (PMID 30627156, 2018). "RT-PCR and IHC of five corticotroph adenomas congruently showed no detection of SSTR3 and SSTR4 while mRNA and IHC levels for SSTR5 were high." (PMID 30627156, 2018).
energy metabolism disorders (1 paper, 2026). "Subsequent RNA sequencing and pathway enrichment analyses revealed that the loss of SSTR4 altered the effects of TAN from extracellular matrix remodeling to disruption of calcium homeostasis and energy metabolism disorders, elucidating the mechanism underlying the enhanced antitumor activity." (PMID 41596716, 2026).
Fibroadenoma (1 paper, 2024). A benign tumor of the breast characterized by the presence of stromal and epithelial elements. "In fibroadenoma and phyllodes tissues, particularly SSTR4 and 5, gene expressions were observed to be higher than in PanNET." (PMID 39767203, 2024).
hamartoma (1 paper, 2020). A benign and excessive tumor-like growth of mature cells and normal tissues which grow in a disorganized pattern. "Among all nine SSTR-4-positive samples, two were rhabdomyosarcomas, two specimens were ALL, one was HL, one was teratoma type, one histologically was defined as hamartoma, one as HS, and one was chronic benign neutropenia." (PMID 33297556, 2020). "Among the nine SSTR-4 positive samples, two were RMS, two ALL, one was HL, one teratoma-type, one histologically was defined as hamartoma, one as HS, and one as chronic benign neutropenia." (PMID 33297556, 2020).
somatotropinomas (1 paper, 2024). "Somatostatin receptor subtype 5 mRNA was highest in somatotropinomas, followed by SSTR2 > SSTR3 >> SSTR1 >>> SSTR4." (PMID 39202532, 2024).
thyroid tumor (1 paper, 2022). A benign or malignant neoplasm affecting the thyroid gland. "These “fourth-generation analogs” have been reported to show very high affinity for SSTR2, SSTR3, and SSTR5 and intermediate-high affinity for SSTR4, which possibly make them good candidates for thyroid tumor cells that express high levels of SSTR3 or 5, despite low expression of SSTR2." (PMID 35453992, 2022).
tumor (22 papers, 2016 to 2026). "For both, SSTR3 and SSTR4, the few cases with higher expressions had a higher rate of tumor recurrences with 33.2% (p = 0.0351) and 37.5% (p = 0.0390), respectively." (PMID 34601710, 2022). "Moreover, low SSTR4 expression correlates with advanced tumor stage, remodeling of the immune microenvironment, and decreased overall survival in patients with LUAD." (PMID 41596716, 2026). "Collectively, these findings establish SSTR4 as a critical tumor suppressor and prognostic biomarker in LUAD and highlight the therapeutic potential of targeting the TAN-SSTR4 signaling axis." (PMID 41596716, 2026). "For lung NECs, the predominant SSTRs are SSTR2A and SSTR1, with SSTR4 and SSTR5 less frequently expressed, depending on the degree of differentiation of the tumor." (PMID 39329930, 2024). "SSTR1 was expressed in three (75%), SSTR3 in two (50%), SSTR4 in 0% and SSTR5 in 0% of the GLP-1R-negative tumours, compared to eleven (23%) (p = 0.055), fifteen (31%) (p = 0.589), 0% and three (6%) (p = 1.000) in GLP-1R-positive tumours, respectively." (PMID 37894845, 2023). "Univariate analysis demonstrated a higher rate of tumor recurrence for increased expression scores for SSTR2A, SSTR3, and SSTR4 (p = 0.0312, p = 0.0351, and p = 0.0390, respectively), while high expression levels of SSTR1 showed less frequent tumor recurrences (p = 0.0012)." (PMID 34601710, 2022). "It has earlier been demonstrated in a mouse tumor model that the endocytosed receptors are predominantly recycled, and that the de novo synthesis is low for SSTR1- SSTR4, whereas SSTR5 is the only receptor which is stored intracellularly and can rapidly be recruited." (PMID 34822040, 2021). "However, SSTR4 is not the main receptor in most tumours and future studies will be of great interest to attest the role of SSTR4 in cancer of different origin." (PMID 38203605, 2023). "Within the 18 tumour specimens, SSTR2A showed the highest immunoreactivity with a median IRS of 8, while SSTR1, SSTR2B und SSTR5 had a median IRS of 3 and SSTR3 und SSTR4 showed no immunoreactivity (median IRS = 0)." (PMID 37707754, 2023). "In addition, Somatostatin Receptor 4 (SSTR4), which we found to be more highly expressed in Spalax tissues, could inhibit the proliferation of normal cells or tumor cells and suppress the formation of tumor vessels via releasing hormone-inhibiting tumor growth." (PMID 30621584, 2019).
cancer (8 papers, 2014 to 2023). A tumor composed of atypical neoplastic, often pleomorphic cells that invade other tissues. "FAM159B co-localised with RGS9, D2R, SSTR4, and SSTR5 in the four cancer cell lines to a different extent." (PMID 36362289, 2022).
SSTR4 also shares sentences with these, for which no sentence is quoted: mood disorder (3 papers); colon carcinoma (2); gastric cancer (2); malignant melanomas (2); mental illnesses (2); pheochromocytoma (2); thyroid cancer (2); adenocarcinoma (1); alcoholism (1); anaplastic thyroid carcinomas (1); Arthritis (1); bipolar disorder (1); bone cancer (1); bronchiectasis (1); Cerebral ischemia (1); epilepsy (1); glioblastoma (1); Head and neck tumor (1); insulinomas (1); leukemia (1); lung carcinoma (1); lymphoma (1); malignant pleural mesothelioma (1); neuroendocrine neoplasm (1); neutropenia (1); pancreatic adenocarcinoma (1); paraganglioma (1); parathyroid adenomas (1); pituitary Cushing's disease (1); pneumonia (1).
A further 8 diseases each share a sentence with SSTR4 in 1 paper.